HIF1A (hypoxia inducible factor 1 subunit alpha)
Diseases named in the same sentence as HIF1A in open-access papers (continued):
Sharing a sentence is not in itself a finding about the gene and the disease.
colon carcinoma (continued). "Consistent with our results, studies have shown that HIF-1α activation could be correlated with a decrease in ZO-1 level in b.End.3 endothelial cells or in the increase of P-gp expression in colon carcinoma cells." (PMID 36902491, 2023). "While there is initial evidence of resveratrol-binding HIF-1α restriction in HT-29 and LoVo colon carcinoma cells, thus exploring of the effects of resveratrol on HIF-1α signaling in HCT-116 and 5-FU-resistant HCT-116R CRC cells offers particular scientific interest." (PMID 36902421, 2023). "Mechanistically, we show that knockout of USP10 in different colon cancer cells causes an elevation in HIF-1α but not HIF-2α protein levels under both normoxic and hypoxic conditions." (PMID 37371055, 2023). "Furthermore, USP10 knockout in HCT116 and COLO320 colon cancer cells led to higher HIF-1α protein levels under both normoxia and hypoxia." (PMID 37371055, 2023). "We also found that irradiation induced the expression of HIF-1α in colon cancer cells and hypoxia." (PMID 37198556, 2023). "Interestingly, osthole also partially reduced the overexpression of HIF1α, and this effect has been previously reported in hypoxic colon cancer cells." (PMID 37237888, 2023). "In addition, VMP1 is involved in the resistance to photodynamic therapy in colon cancer cells, in which its expression is triggered by the transcription factor hypoxia-inducible factor 1 alpha (HIF-1α)." (PMID 37629161, 2023). "To evaluate whether HIF-2 stress signaling is regulated by Acss2 in colon cancer derived cell lines, we first asked whether HIF-1α and HIF-2α were present in HCT116 and HT29 cell lines and whether their levels were affected by oxygen or glucose deprivation." (PMID 36862715, 2023). "Given that HIF-1α may stimulate miR-155–5p in colon cancer cells, we hypothesized that the possible link of HIF-1α/miR-155–5p could accelerate OTA-induced ER stress and fibrosis in kidney." (PMID 36714464, 2023). "Furthermore, both glycolytic pathway utilisation and HIF-1α can be altered by NO and were shown to be increased in macrophages within colon tumours in the RNA-seq reanalysis." (PMID 35660630, 2022). "Interestingly, miR-22 was shown to modulate HIF1a expression in human colon cancer cells where overexpression of miR-22 repressed HIF1a expression and knockdown of endogenous miR-22 enhanced HIF1a expression conversely." (PMID 36359830, 2022). "Moreover, in Ls174T (colon cancer) cells, hypoxic induction of Slc4a4 is regulated by HIF-1α and sequences for HIF-1α binding sites were found in the Slc4a4 promoter." (PMID 36012235, 2022). "YTHDC2 contributes to colon tumor metastasis by promoting the translation of HIF-1α." (PMID 35155557, 2022). "Furthermore, it was demonstrated that ZFP91 promotes colon cancer cell proliferation by activating HIF-1α via NF-κB/p65 and leading to a significant increase in the proportion of cells in the S phase." (PMID 36358661, 2022). "Downregulation of the YTHDC2 gene can significantly inhibit the translation of tumor metastasis-related genes, such as hypoxia-inducible factor-1alpha (HIF-1α), and the high expression of this molecule is positively correlated with tumor stage and colon cancer metastasis." (PMID 35614935, 2022). "HIF1A promotes G1 arrest of colon cancer cells by down-regulating c-Myc-activated gene expressions." (PMID 36139919, 2022). "Moreover, in vitro and in vivo investigations on colon cancer showed that wogonin inhibited HIF-1α, HK2, PDK1, and LDHA expression." (PMID 36339566, 2022). "Moreover, salternamide A, a Streptomyces-derived natural product, inhibits hypoxia-promoted HIF1A overexpression and triggers apoptosis of colon cancer cells." (PMID 36139919, 2022). "Furthermore, sulforaphane blocks the angiogenesis of colon cancer cells by down-regulating HIF1A and VEGF expression." (PMID 36139919, 2022).
colon carcinoma (continued). "Furthermore, the hypoxia-inducible factor 1-alpha (HIF-1α)/vacuole membrane protein 1 (VMP1) axis mediates therapeutic resistance in colon cancer cells." (PMID 35965522, 2022). "Furthermore, by means of data mining of CRC patients and analysis of interaction networks, which are described in detail in the following subtopic, we corroborated that HIF-1α has a high clinical value in colon tumor progression." (PMID 35741024, 2022). "Moreover, brusatol can also inhibit HIF1α accumulation under hypoxia in colon carcinoma cells, abrogating its signaling pathway." (PMID 33916438, 2021). "Moreover, it has been found that miR-526b-3p serves as a cancer inhibitor by regulating HIF-1α in colon cancer." (PMID 35004266, 2021). "Further, isorhamnetin and melatonin treatment could reduce HIF-1α expression via suppressing the ROS level, contributing to the inhibition of invasion and migration of human colon cancer cells." (PMID 33542787, 2021). "Drug resistance may be induced by HIF-1α-mediated P-gp expression which has been investigated in a variety of tumor cells, including mammary gland carcinoma and colon cancer cells." (PMID 34124226, 2021). "VB significantly inhibits tumor cell metastasis and invasion by inhibiting Rac-1, hypoxia inducible factor-1α (HIF-1α), and Zeb-1 signaling pathways, which may be the most metastatic phenotype of colon cancer-suitable drug candidates." (PMID 33768139, 2021). "In addition, LOX is involved in the hypoxic upregulation of HIF-1α, while LOX and HIF-1α potentiate each other to foster colon tumor progression through the PI3K/Akt signaling pathway." (PMID 34815382, 2021). "It has been confirmed that Piezo1 induced the expression of HIF‐1α in colon cancer cells." (PMID 33439514, 2021). "Notably, colon cancer cells in the hypoxic layer showed increased expression of the hypoxic marker, HIF-1α (hypoxia-induced factor 1α), and enhanced chemo- and radioresistance." (PMID 34298763, 2021). "A novel HIF-1α/VMP1-autophagy pathway has also been reported in colon cancer cells." (PMID 33637686, 2021). "SFN also inhibited VEGF expression, suggesting that SFN may hinder colon cancer progression and angiogenesis by downregulating the expression of HIF-1α and VEGF." (PMID 34638282, 2021). "Moreover, by inducing expression of the major intracellular enzyme with deglutathionylase activity, glutaredoxin 1, Jeon and coworkers confirmed the relevance of HIF-1α glutathionylation for its activity in colon cancer cells." (PMID 33937322, 2021). "Interestingly, among the complex changes of cellular redox regulation induced by intratumoral hypoxia, increase in the S-glutathionylation of HIF-1α and its expression in colon cancer cells has been demonstrated recently." (PMID 33937322, 2021). "To test whether Cyr61 affects the tumor growth of colon carcinoma, we intratumorally injected recombinant Cyr61 into HIF-1α-KD tumors." (PMID 33142239, 2020). "It is described that colon carcinomas exhibit increased nuclear expression of HIF1-α." (PMID 32231135, 2020). "In the present study, it was speculated that the circRNA_100859-miR-217-HIF-1α axis may promote colon cancer progression and that HIF-1α may be a potentially novel therapeutic target for colon cancer." (PMID 32644049, 2020). "Furthermore, multivariate Cox regression analysis revealed that high circRNA_100859, low miR-217, high HIF-1α expression levels as well as histological grade were a poor prognostic factors for colon cancer." (PMID 32644049, 2020). "In contrast, some studies suggested that ouabain or digoxin may upregulate HIF-1α in colon cancer cells and the kidney tubules." (PMID 33101052, 2020).
colon carcinoma (continued). "In addition, miR-20b inhibits the proliferation, migration and invasion of osteosarcoma cells and colon cancer cells by targeting HIF-1α and cyclinD1, respectively." (PMID 33680910, 2020). "Therefore, in our study, we explored the regulatory relationships among Piezo1, MCU, and HIF-1α in colon cancer metastasis." (PMID 32152662, 2020). "However, in colon cancer HIF-1α and HIF-2α apparently have different roles, regulating cell proliferation and anchor-independent growth, respectively." (PMID 33142239, 2020). "Interestingly, a previous study found that HIF-1α regulates the transcription of DcR2 in human colon cancer cell lines." (PMID 32848609, 2020). "Also, all 50 colon cancer cases were divided into high and low circRNA_100859, miR-217, and HIF-1α expression groups by using the median circRNA_100859, miR-217, and HIF-1α expression values, respectively." (PMID 32644049, 2020). "Furthermore, in order to determine the interaction between the circRNA_100859-miR-217 axis and HIF-1α, and the roles of the circRNA_100859-miR-217-HIF-1α axis in colon cancer progression, rescue assays were performed." (PMID 32644049, 2020). "Additionally, RT-qPCR demonstrated that HIF-1α mRNA was markedly overexpressed in colon cancer tissues (n=50) (P<0.05), and Pearson’s analysis indicated that there was negative correlation between miR-217 and HIF-1α mRNA expression levels (P<0.05)." (PMID 32644049, 2020). "In the present study, circRNA expression profiles were screened and it was found that circRNA_100859 was overexpressed in colon cancer tissues, and circRNA_100859 promoted colon cancer progression by sponging miR-217 to upregulate hypoxia-inducible factor (HIF)-1α expression levels." (PMID 32644049, 2020). "We also found that HIF-1α was up-regulated in colon cancer tissues." (PMID 32152662, 2020). "Knockdown of HIF-1α decreased the growth rate of HCT116 and SW620 cells, which confirm that HIF-1α could be a therapeutic target for decelerating colon cancer cell growth." (PMID 31849679, 2019). "To this end, we created a stable knockdown of HIF-1α or HIF-2α in colon cancer cells." (PMID 31151160, 2019). "LPA induces HIF-1α expression in several types of cancer cells, including colon cancer cells." (PMID 31323936, 2019). "Matrine could be further developed as an antitumor agent targeting the HIF-1α-mediated Warburg effect for colon cancer treatment." (PMID 31849679, 2019). "Association analysis between HIF-1α, MDR1 and LAPTM4B expression in colon cancer blood specimens." (PMID 30746305, 2019). "Moreover, this inhibitory effect of matrine was significantly attenuated when HIF-1α was knocked down or exogenous overexpressed in colon cancer cells." (PMID 31849679, 2019). "Interestingly, HIF-2α promotes cell proliferation in renal-cell adenocarcinoma cells (WT8, 786 –O RCC), whereas HIF-1α inhibits the proliferation of HCT116 colon carcinoma cells at 0.5% O29." (PMID 29426911, 2018). "RNA helicase YTHDC2 acts as a promoter in colon cancer metastasis by enhancing the translation of hypoxia-inducible factor-1alpha (HIF-1α) gene, which could promote EMT via the transcription factor Twist1." (PMID 30062093, 2018). "Also, in human colon cancer cells, HIF-1α was shown to inhibit BRCA1 activity indirectly by counteracting C-MYC under hypoxic and normoxic conditions, while BRCA1 was found to enhance hypoxia-induced stabilization of HIF-1." (PMID 29755367, 2018). "Importantly, HIF-1α mutant mice harboring MC38 colon carcinoma tumors had a significantly inhibited response to αPD-1 and αCTLA4 combinatorial antibody-based immunotherapy relative to control WT littermates." (PMID 29136509, 2017). "Overall, our data indicated that miR-675-5p promotes tumour progression in colon carcinoma regulating the expression of EMT genes by at least two independent mechanisms: the activation of the transcription factor HIF1α and the inhibition of the repressor factor DDB2." (PMID 28061476, 2017).
colon carcinoma (continued). "Interestingly, FOXO3a activation blocks the hypoxia-dependent increase in ROS in colon cancer cells and prevents HIF-1α stabilization." (PMID 29250065, 2017). "Pro was referred as a HIF-1α inducing agent in colon cancer cell line RKO." (PMID 28526934, 2017). "In xenograft models of colon cancer, tumors formed by cells with stable knockdown of Nrf2 developed fewer blood vessels, and this was related to reduced expression of hypoxia inducible factor (HIF)-1α." (PMID 28383481, 2017). "Thus, we concluded that ZFP91 is able to activate HIF-1α transcription through interacting with NF-κB/p65 in colon cancer cells." (PMID 27144516, 2016). "Our data suggests that ZFP91 promotes the proliferation of colon cancer cells through HIF-1α." (PMID 27144516, 2016). "We found that ZFP91 upregulated HIF-1α at the levels of promoter and protein in colon cancer cells." (PMID 27144516, 2016). "Next, we examined whether HIF-1α involved in the promotion of proliferation of colon cancer cells mediated by ZFP91." (PMID 27144516, 2016). "Thus, we concluded that ZFP91 activates transcriptional coregulatory protein HIF-1α through transcription factor NF-κB/p65 in the promotion of proliferation and tumorigenesis in colon cancer cell." (PMID 27144516, 2016). "One of them, investigating the human prostate, tongue and colon carcinoma cells exposed to hypoxia showed that SFN can interfere with the HIF-1 pathway through decreasing the HIF-1α protein level and reducing the expression of the pro-angiogenic growth factor VEGF." (PMID 25955133, 2015). "We have shown previously that HIF1α is critical for aerobic growth of colon cancer cells." (PMID 26352431, 2015). "The last reference gene, the glycolysis enzyme phosphoglycerate kinase 1 (PGK1), is a target gene of both the myc oncogene pathway and the hypoxia inducible factor 1α (HIF-1α) and is therefore considered as a marker gene for a number of malignant tissues such as kidney cancer or colon cancer." (PMID 26468005, 2015). "Our previous study showed that HIF-1α protein expression is correlated with P-gp expression in colon carcinoma tissues and colon cancer cell lines, and HIF-1α and MDR1 mRNAs were found to be significantly higher in the same cells under hypoxic conditions than under normoxic conditions." (PMID 24901645, 2014). "Our previous study showed that HIF-1α protein expression is correlated with MDR1/P-gp expression in colon carcinoma tissue and a colon cancer cell line, and mRNA expression levels of HIF-1α and MDR1 are significantly higher in the same type of cells in hypoxic conditions than in normoxic conditions." (PMID 24901645, 2014). "Furthermore, MSCs have been shown to promote tumor growth by enhancing tumor angiogenesis via HIF-1α-VEGF signalling pathway in the colon cancer model." (PMID 24872873, 2014). "In hypoxic microenvironment, we assume that HIF-1α may directly induce the expression of MDR1/P-gp which leads to MDR, and the reversal of colon cancer MDR can be achieved when HIF-1α expression is specifically inhibited." (PMID 24901645, 2014). "Interestingly, a HIF1A transcription factor selectively regulates infiltrating MDSC but does not contribute to the homeostasis of CD11b+ cells from spleens in c26GM colon cancer." (PMID 25294811, 2014). "To demonstrate that elevation of FGF9 protein in colon cancer cells was due to hypoxia-mediated translational upregulation, we stained HIF-1α, a marker of hypoxic cells, in the same 40 pairs of samples and found that HIF-1α was upregulated in the colon cancer cells." (PMID 24334956, 2014). "A study of NEDD9 in colon cancer cells has confirmed that its induction under hypoxic conditions is regulated by hypoxia-inducible factor 1α (HIF1α) and in turn modulates the interaction between HIF1α and its transcriptional coactivator p300." (PMID 25594051, 2014). "15-LOX-1 reexpression in colon cancer cells reduced HIF-1α mRNA to variable degrees." (PMID 24634093, 2014).
colon carcinoma (continued). "It is well known that HIF1α levels are higher in breast and colon cancer metastases." (PMID 25079072, 2014). "It remains unclear whether and how HIF-1α is involved in MDR in colon cancer via the interaction of MDR1/P-gp." (PMID 24901645, 2014). "In this study, we analyzed the activity of five putative promoters (P1–P5) of CD133 in human embryonic kidney (HEK) 293 cells and colon cancer cell line WiDr, and found that the activity of promoters, particularly of P5, is elevated by overexpression of hypoxia-inducible factors (HIF-1α and HIF-2α)." (PMID 23840432, 2013). "Thus, there is a possibility that the digoxin-like molecule CBF reduces HIF-1α levels in colon cancer cell lines as well." (PMID 23818933, 2013). "RT-PCR was used to investigate HIF-1α mRNA expression in colon cancer cell lines." (PMID 23181101, 2012). "Investigation of HIF-1α mRNA expression in colon cancer cell lines and in cells cultured under identical conditions with added PSK revealed a significant decrease in expression, as well as a decrease in angiogenic growth factors and related genes in PSK-treated colon cancer cell lines." (PMID 23181101, 2012). "We now identify HIF-1α as a target for miR-22 in a colon cancer cell line." (PMID 21629773, 2011). "In all, 39% (60 out of 155) and 53% (85 out of 159) of colon cancers were positive for nuclear HIF-1α and HIF-2α expression, respectively; 21% of cases (31 out of 147) expressed both HIF-1α and HIF-2α and 51% of cases (75 out of 147) expressed either HIF-1α or HIF-2α." (PMID 19844231, 2009). "In survival analyses, the absence of an observed prognostic association for HIF-1α in colon cancer is consistent with previous reports." (PMID 19844231, 2009). "Therefore, we further investigated whether fructose-induced upregulation of VEGF expression was related to ROS and HIF1α in colon cancer cells." (PMID 37507736, 2023). "Furthermore, recent studies suggested that HIF1a protein can increase Gal-1 expression in colon cancer by binding to DNA to promote transcription of the Gal-1 gene, whereas shRNA-mediated silencing of HIF1a expression antagonized hypoxia-induced Gal-1 expression." (PMID 36359830, 2022). "What is more, ZFP91 can not only activate HIF-1α through NF-κB/p65 but also positively regulate the production of inflammatory cytokine IL-1β in macrophages by activating the MAPKs and atypical caspase-8 inflammasome, which advances the proliferation and tumorigenesis of colon cancer." (PMID 36358661, 2022). "Moreover, the angiogenesis inhibition of cryptotanshinone (CPT) was implicated in multi-signaling, including Wnt/β-catenin/VEGF axis, VEGFR2 and its downstream Src/FAK, ERK1/2 in HUVECs, while it leads to the downregulation of PI3K/Akt/mTOR signaling and HIF-1α in CT26 colon cancer cells." (PMID 35784750, 2022). "Therefore, overexpression of TRPC5 promotes the migration and proliferation of colon cancer cells through the TRPC5/HIF-1α/Twist signaling pathway, and TRPC5 and HIF-1α may become potential therapeutic targets for colon cancer." (PMID 36187789, 2022). "Furthermore, we demonstrated that HIF1α binds to LIN28A in the colon cancer cells by ChIP assay." (PMID 33665193, 2021). "Moreover, vanillic acid has suppressed human colon cancer HCT116 cells via HIF-1α inhibition." (PMID 33445792, 2021). "Moreover, low levels of NO are required for HIF1α stabilization in HCT116 colon cancer cells." (PMID 32825247, 2020). "Moreover, MTT assay shows that overexpression of HIF-1α could overcome a part of the toxicity of matrine on colon cancer cells." (PMID 31849679, 2019). "Thus, we hypothesized that some transcriptional factors including HIF-1α regulate PrPc gene expression in colon carcinoma cells during hypoxia." (PMID 25742790, 2015). "Thus, we suggest that up-regulating HIF-1α protein may modulate PrPc expression in rapidly growing colon cancers." (PMID 25742790, 2015).